PGK1 (phosphoglycerate kinase 1)
Diseases named in the same sentence as PGK1 in open-access papers (continued):
Sharing a sentence is not in itself a finding about the gene and the disease.
breast carcinoma (continued). "Herein, we conducted a systematic analysis to uncover the clinical implication of PGK1 deregulation in breast cancer." (PMID 34790279, 2021). "PGK1 was also demonstrated to be a target gene that modulated cell viability, proliferation, invasion and apoptosis in breast cancer." (PMID 33747900, 2021). "The current analysis showed that PGK1 expression was lower in CDH-mutant than wild-type in breast cancer patients." (PMID 34291087, 2021). "In this study, we analyzed data from various online databases and revealed that the mRNA and protein expression levels of PGK1 were up-regulated in various clinicopathologic types of breast cancer." (PMID 34291087, 2021). "Our previous study revealed a correlation between high level of PGK1 expression and poor prognosis in breast cancer." (PMID 33747900, 2021). "ROC curves were conducted for assessing the performance of PGK1 in prediction of breast cancer prognosis." (PMID 34790279, 2021). "In this study, we elucidated that PGK1 shaped an inflamed tumor microenvironment in line with the evidence that PGK1 displayed positive correlations to the immunological status of tumor microenvironment in breast cancer." (PMID 34790279, 2021). "PGK1 was found to be an independent prognostic factor in determining breast cancer by univariate and multivariate cox regression." (PMID 34291087, 2021). "PGK1 promotes the breast cancer cell growth and the lactic acid generation, which is the end product of glycolysis." (PMID 34291087, 2021). "Existing data analysis showed that elevated expression of PGK1 was related with short OS (Overall Survival) in diverse types of cancer or PGK1 combined with other genes to predicting the survival of patients with breast cancer." (PMID 34291087, 2021). "Second, in-depth experiments will be presented for determining the expression profiling of PGK1 in breast cancer cells as well as tumor-infiltrating immune cells." (PMID 34790279, 2021). "As a result, PGK1 expression exhibited marked upregulation in breast cancer in comparison to normal specimens (p = 2e − 184)." (PMID 34790279, 2021). "This demonstrated that PGK1 possessed the potential as a reliable prognostic predictor of breast cancer." (PMID 34790279, 2021). "Together, these results indicated that PGK1 mRNA expression was up-regulated in human breast cancer." (PMID 34291087, 2021). "We previously showed that elevated mRNA and protein expression levels of PGK1 were detected in breast cancer tissues compared with normal breast tissues." (PMID 33747900, 2021). "The PGK1-based model of breast cancer showed moderate predictive ability (AUC = 0.716, 0.682, and 0.678 for 1, 3, and 5-years survival)." (PMID 34291087, 2021). "Through GSEA method, we investigated biological pathways and hallmarks of cancer involved in PGK1 through comparison of up- and downregulated PGK1 groups across breast cancer samples from the TCGA dataset." (PMID 34790279, 2021). "Here, we analyzed data from the Oncomine database, Breast cancer Gene-Expression Miner v4.5, TNMplot, MuTarget, PrognoScan database, and clinical bioinformatics to investigate PGK1 expression distribution and prognostic value in breast cancer patients." (PMID 34291087, 2021). "The correlation between PGK1 mRNA expression and the clinicopathological parameters of breast carcinoma." (PMID 34291087, 2021). "Collectively, PGK1 was capable of robustly predicting the prognosis and response to cancer immunotherapy in breast cancer." (PMID 34790279, 2021). "Due to HIF-1/PGK1-mediated epithelial-mesenchymal transformation (EMT), PGK1 is associated with the ability of cancer cells to metastasize, and the high expression of PGK1 is related to the inferior survival outcome of breast cancer patients." (PMID 33941139, 2021). "Fourth, in vitro and in vivo experiments will be performed to explore the potential function of PGK1 dysregulation in the proliferation, migration, and invasion of breast cancer." (PMID 34790279, 2021).
breast carcinoma (continued). "In conclusion, our results indicate the overexpression of PGK1 at the transcriptional and protein levels in breast cancer patients." (PMID 34291087, 2021). "Our study revealed that the mRNA and protein expression levels of PGK1 were up-regulated in various clinicopathologic types of breast cancer." (PMID 34291087, 2021). "In the TCGA cohort, we compared the mRNA expression of PGK1 in normal (n = 572) and breast cancer (n = 1097) tissues." (PMID 34790279, 2021). "In our analysis of PGK1 correlated signaling pathways in breast cancer, GeneMANIA and Web Gestalt analysis indicates PGK1 is involved in glycolysis/gluconeogenesis, biosynthesis of amino acids, HIF-signaling pathway, carbon metabolism and metabolic pathways." (PMID 34291087, 2021). "Herein, we observed the positive associations of PGK1 with TMB and MSI across pan-cancer, especially breast cancer, indicative of the potential of PGK1 as an immune response predictor." (PMID 34790279, 2021). "Using the GEPIA2 tool, we evaluated the expression of PGK1 mRNA across distinct pathological stages (stage I-X) across breast cancer patients." (PMID 34790279, 2021). "It was proven that PGK1 plays a vital role in the proliferation, migration, and invasion of human breast cancer." (PMID 34291087, 2021). "Taken together, these data suggest that the miR-16-1-3p/PGK1 axis plays an important pathological role in human breast cancer." (PMID 33344462, 2020). "PGK1 expression has previously been described in various malignancies and was recently demonstrated to correlate to poor prognosis in breast cancer." (PMID 32272779, 2020). "HER2-enriched and Basal subtypes had the highest fraction of TILs, which was in line with PGK1 expression in breast cancer subtypes." (PMID 32070368, 2020). "PGK1 is a survival biomarker for breast cancer and it can promote invasion via modulating the EMT process." (PMID 32489020, 2020). "Since miR-16-1-3p inhibits PGK1 expression and suppresses breast cancer lung metastasis, we evaluated the expression of miR-16-1-3p and PGK1 by MISH and IHC, respectively, in 91 human breast cancer samples." (PMID 33344462, 2020). "Our findings provide clues regarding the role of miR-16-1-3p as a tumor suppressor in breast cancer through PGK1 suppression." (PMID 33344462, 2020). "MiR-16-1-3p plays an important role in regulation of PGK1-mediated Warburg effect and breast cancer cell proliferation, migration, invasion, and metastasis." (PMID 33344462, 2020). "In breast cancer patients, miR-16-1-3p expression is negatively correlated with PGK1 expression and breast cancer lung metastasis." (PMID 33344462, 2020). "Breast cancer patients with decreased miR-16-1-3p expression had shorter disease-free survival, and breast cancer patients with decreased PGK1 expression had longer disease-free survival." (PMID 33344462, 2020). "PGK1 was up-regulated in various cancers, such as multi-drug resistant ovarian cancer, breast cancer, renal cancer, pancreatic carcinoma, and squamous cell carcinoma." (PMID 33053689, 2020). "Many studies show that PGK1 is highly expressed in various cancers, such as breast cancer, liver cancer, and colon cancer." (PMID 33344462, 2020). "Aerobic glycolysis regulated by the miR-16-1-3p/PGK1 axis is critical for modulating breast cancer cell proliferation, migration, invasion and metastasis in vitro and in vivo." (PMID 33344462, 2020). "Taken together, these results suggest that miR-16-1-3p inhibits breast cancer cell proliferation, migration and invasion by repressing PGK1 expression." (PMID 33344462, 2020). "Our study revealed for the first time that miR-16-1-3p inhibits tumor glycolysis by targeting PGK1 both in vitro and in vivo, thereby repressing breast cancer cell proliferation, migration, invasion, and metastasis." (PMID 33344462, 2020).
breast carcinoma (continued). "In breast cancer, the expression of PGK1 has been shown to be elevated in malignant tissues compared with corresponding normal tissues and associated with poor clinical outcomes and chemoresistance." (PMID 32276500, 2020). "Given the important role of PGK1 in the glycolytic pathway and breast cancer progression, we selected PGK1 for further study." (PMID 32070368, 2020). "The 1096 breast cancer patients derived from TCGA were then divided into two groups based on the median expression of PGK1." (PMID 32070368, 2020). "The potential of PGK1 as a target for the treatment of breast cancer was found by analyzing publicly available datasets." (PMID 32276500, 2020). "Recent studies have shown that the protein level of PGK1 was elevated in breast cancer, astrocytoma, metastatic colon cancer, and pancreatic ductal adenocarcinoma; its mRNA levels were increased in gastric cancer." (PMID 31578148, 2019). "The PGK1 is elevated in breast cancer tissues compared to normal tissues, and it’s expression is dependent on the oxygen tension." (PMID 31558821, 2019). "The elevated levels of PGK1 protein, detected in the serum of patients affected by pancreatic cancer and in breast cancer tissues, suggest a plausible use of PGK1 as a cancer biomarker." (PMID 29995887, 2018). "PGK1 expression is upregulated in human breast cancer, pancreatic ductal adenocarcinoma, radio-resistant astrocytoma, metastatic gastric cancer, and hepatocellular carcinoma cells." (PMID 29416645, 2018). "PGK1 is a predictor of poor survival and a novel prognostic biomarker of chemoresistance to paclitaxel treatment in breast cancer." (PMID 28749413, 2017). "PGK1 over-expression has been shown to correlate with the tumorigenesis in pancreatic ductal adenocarcinoma, liver cancer and breast cancer." (PMID 28903403, 2017). "Proto-oncogene c-MYC as an upstream regulator links to the tumor-secreted protein PGK1 in the process of breast cancer development." (PMID 28749413, 2017). "A recent analysis of the prognostic factors in breast cancer has highlighted the importance of a glycolytic enzyme PGK1 and tumor glycolysis in the prognostic value of stress signatures." (PMID 20824128, 2010). "Additionally, PGK1 protein expression level was significantly upregulated in breast cancer tissues and cells." (PMID 40771921, 2025). "In conclusion, the advancements in research on the glycolytic pathway and the glycolysis-related gene PGK1 in the context of breast cancer under hypoxic conditions offer valuable insights into the mechanisms and therapeutic targets of metabolic reprogramming in breast cancer." (PMID 39590319, 2024). "However, the precise role of PGK1 in the pathogenesis of breast cancer remains inadequately understood." (PMID 39590319, 2024). "Future investigations should delve deeper into the glycolytic pathway and the intricate regulatory mechanisms of PGK1 in breast cancer progression, with the aim of providing a more robust scientific foundation for personalized treatment and prognosis evaluation in breast cancer." (PMID 39590319, 2024). "Studies have shown that PGK1 is a promising therapeutic target for breast cancer treatment." (PMID 39770478, 2024). "Furthermore, activation of the MYC/PGK1 pathway has been shown to amplify the Warburg effect in breast cancer, which in turn contributes to the initiation and progression of the disease." (PMID 39590319, 2024). "PGK1 is up-regulated in breast cancer and is a promising therapeutic target." (PMID 39770478, 2024). "Furthermore, PGK1 can be detected in the peripheral blood of patients, suggesting its potential as a highly promising biomarker for breast cancer screening." (PMID 39590319, 2024). "This suggests that downregulating the expression of PGK1 could be pivotal in the treatment of breast cancer." (PMID 39590319, 2024).
breast carcinoma (continued). "Furthermore, treatment with the specific inhibitor Herceptin in HER-2-positive breast cancer has been shown to markedly reduce PGK1 protein expression, thereby effectively inhibiting the proliferation of breast cancer cells." (PMID 39590319, 2024). "Several malignancies including prostate cancer, breast cancer, pancreatic ductal adenocarcinoma, multidrug resistant ovarian cancer, and metastatic gastric cancer, have all been shown to exhibit an increased expression of PGK1." (PMID 37644393, 2023). "The inhibition of PGK1 could significantly reverse the epithelial-mesenchymal transformation process in the breast cancer." (PMID 35559258, 2022). "High PGK1 expression presented shorter survival in breast cancer than low PGK1 expression." (PMID 33747900, 2021). "Collectively, PGK1 was in relation to an inflamed microenvironment in breast cancer." (PMID 34790279, 2021). "Based on our analysis, PGK1 may be an independent prognostic factor for lung cancer and breast cancer." (PMID 34091600, 2021). "In addition, PGK1 high expression was also representing higher tumor stage, which disclosed that PGK1 was correlated with tumor metastasis, progression and occurrence of breast cancer." (PMID 34291087, 2021). "This study suggested that PGK1 may act as a suitable candidate for the prediction of breast cancer prognosis." (PMID 34790279, 2021). "In addition, the role of miR-16-1-3p as a tumor suppressor in breast cancer through phosphoglycerate kinase 1 (PGK1) suppression was investigated." (PMID 34703648, 2021). "In summary, PGK1 could be a potential target in the development of anti-PGK1 therapeutics and an efficient marker for the prognosis of breast cancer." (PMID 34291087, 2021). "Nevertheless, the role of PGK1 in breast cancer is needed to be thoroughly investigated." (PMID 34790279, 2021). "In addition, bc-GenExMiner 4.5 was used to investigate the expression profile of PGK1 across PAM50 breast cancer subtypes based on different clinicopathological parameters." (PMID 34291087, 2021). "The role of PGK1 in the prediction of breast cancer prognosis was also evaluated." (PMID 34790279, 2021). "Moreover, we found that the protein expression of PGK1 was higher in breast cancer tissues than in normal tissues by HPA." (PMID 34291087, 2021). "PGK1-coupled HSP90 may stabilize GSK3β expression to modulate the stemness features in breast cancer." (PMID 34790279, 2021). "We also demonstrated that overexpression of PGK1 might be a prognostic biomarker of chemoresistance to paclitaxel treatment in breast cancer." (PMID 33747900, 2021). "First, we cannot identify the optimal cut-off of PGK1 among breast cancer patients." (PMID 34790279, 2021). "PGK1 was specifically overexpressed in most of cancer types, including breast cancer." (PMID 34790279, 2021). "However, the correlation of PGK1 mRNA and protein expression with clinicopathologic characteristics and prognostic values according to various kinds of breast cancer patient classifications remains unsufficient." (PMID 34291087, 2021). "Collectively, PGK1 exerted a carcinogenic role in most of cancers, especially breast cancer." (PMID 34790279, 2021). "Our previous study showed that PGK1 might be a predictor of poor survival and an immunohistochemical biomarker to predict the sensitivity to paclitaxel treatment in breast cancer." (PMID 33747900, 2021). "This indicated that PGK1 might shape an inflamed phenotype of tumor microenvironment in breast cancer." (PMID 34790279, 2021).
breast carcinoma (continued). "Moreover, patients with breast cancer with high PGK1 expression displayed a significantly shorter overall survival (OS) duration than those with low PGK1 expression levels." (PMID 32276500, 2020). "Next, we examined whether miR-16-1-3p inhibits proliferation, migration and invasion by repressing PGK1 expression in breast cancer cells." (PMID 33344462, 2020). "Importantly, PGK1 knockdown abolished the ability of anti-miR-16-1-3p to increase breast cancer cell proliferation, migration, and invasion." (PMID 33344462, 2020). "Through inhibition of PGK1, miR-16-1-3p suppressed aerobic glycolysis by decreasing glucose uptake, lactate and ATP production, and extracellular acidification rate, and increasing oxygen consumption rate in breast cancer cells." (PMID 33344462, 2020). "In breast cancer patients, the abundance of miR-16-1-3p is inversely related to PGK1 expression." (PMID 33344462, 2020). "In breast cancer specimens, miR-16-1-3p expression is inversely correlated with PGK1 expression." (PMID 33344462, 2020). "PGK1, as an important enzyme in glycolytic pathways, had obvious influence on breast cancer patients’ clinical outcome, which revealed that PGK1 played a critical role in the progression of breast cancer and may be a potential therapeutic target." (PMID 32070368, 2020). "Therefore, the PGK1 inhibitor is a promising candidate for the treatment of breast cancer." (PMID 39770478, 2024). "Zhong chu demonstrated that LINC00926 interacts with PGK1 and promotes its ubiquitination and degradation by binding to the E3 ligase STUB1, which is the first E3 ligase responsible for PGK1 degradation and may be a potential therapeutic target for breast cancer." (PMID 37723547, 2023). "Notably, ROC curves confirmed that PGK1 can robustly predict breast cancer prognosis." (PMID 34790279, 2021). "Furthermore, PGK1 has been revealed to be activated in breast cancer." (PMID 33747900, 2021). "In addition, the increased expression of PGK1 predicted a poor outcome in breast cancer patients." (PMID 33747900, 2021). "However, the role and clinical significance of PGK1 in different pathology subtype of breast cancer remain unclear." (PMID 34291087, 2021). "Moreover, our findings indicated that PGK1 shaped an inflamed tumor microenvironment in breast cancer as well as could predict the clinical response to immunotherapy." (PMID 34790279, 2021). "As reported in the literature, inhibition of PGK1 could suppress aerobic glycolysis by decreasing glucose uptake, lactate and ATP production, extracellular acidification rate, and promoting oxygen consumption rate in breast cancer cells." (PMID 34490098, 2021). "Moreover, PGK1 might shape an inflamed tumor microenvironment in breast cancer as well as possesses the potential to estimate breast cancer prognosis." (PMID 34790279, 2021). "Therefore, up-regulating miR-16-1-3p may provide new treatment ideas for cancer patients, especially breast cancer patients with PGK1 overexpression." (PMID 33344462, 2020). "Therefore, miR-16-1-3p activation may have a positive effect on the treatment of breast cancer patients with PGK1 overexpression." (PMID 33344462, 2020). "PGK1 is up-regulated in breast cancer 35, pancreatic ductal adenocarcinoma 36, and hepatocellular carcinoma 37, while depletion of PGK1 dramatically reduces the proliferation and metastasis of cancer cells, indicating an oncogenic role of PGK1 in tumor progression." (PMID 32042322, 2020). "Next, we explored whether the miR-16-1-3p/PGK1 axis regulates breast cancer metastasis." (PMID 33344462, 2020). "Targeting PGK1 through miR-16-1-3p could be a promising strategy for breast cancer therapy." (PMID 33344462, 2020). "Several solid tumors like prostate cancer, breast cancer, pancreatic ductal adenocarcinoma, multidrug-resistant ovarian cancer and metastatic gastric cancer exhibit an increased expression of glycolytic enzymes such as PGK1 to generate ATP in hypoxic conditions." (PMID 29995887, 2018).